IL4 (interleukin 4)
Diseases named in the same sentence as IL4 in open-access papers (continued):
Sharing a sentence is not in itself a finding about the gene and the disease.
asthma (continued). "For example, the differentiation between asthma, COPD and asthma-COPD overlap encountered in firefighters who cleared debris from WTC relied on measuring eosinophilia and interleukin 4 (IL-4), which increased only in asthma-COPD overlap, and IL-21, which was higher only in isolated asthma and COPD." (PMID 34577834, 2021). "IL-4- and IL-17-producing CD8+ T cells, i.e., T cytotoxic type 2 (Tc2) and T cytotoxic type 17 (Tc17) cells, respectively, are particularly involved in the pathogenesis of asthma." (PMID 34071080, 2021). "While isolated blockade of either IL-4 or IL-13 has not been shown to be effective in treatment of severe asthma, dual blockade of IL-4 and IL-13 has shown promise." (PMID 35126131, 2021). "Moreover, levels of IL-4, IL-13, and IL-17 in BALF were increases in the asthma group relative to the normal group." (PMID 33577738, 2021). "CLCA1 is an IL-4 and IL-13 inducible, STAT6-dependent mediator of chloride ion transport/fluid production and mucin/mucus production and is involved in asthma." (PMID 32431691, 2020). "Moreover, high numbers of dual-positive Th2/Th17 lymphocytes secreting large quantities of IL-4 and IL-17 were detected in BALF from patients with severe asthma." (PMID 33329598, 2020). "In another study, SIRT1 activator (SIRT1720) treatment decreased the eosinophil count and IL-5 and Il-13 levels, but not IL-4 levels in the bronchoalveolar fluid and lung tissue in the ovalbumin-induced asthma mouse model." (PMID 32823491, 2020). "Furthermore, Th2-specific IL-4 and IL-13 cytokines were produced by bronchial epithelial cells via STAT3-dependent allergic inflammation in asthma." (PMID 33374928, 2020). "In our initial report, we demonstrated that doxycycline suppresses C. pneumoniae mediated interferon-gamma responses in PBMC from children with asthma; azithromycin did not decrease IL-4 or IgE responses." (PMID 32511255, 2020). "While asthma involved pathways like NFAT in regulation of the immune response and other lymphocyte activation pathways including signaling through IL-4, IL-8, IL-3 and IL-9 in CD8+ cells, the most prominent pathway in CD4+ cells was VDR/RXR activation signaling." (PMID 32900903, 2020). "Early studies in patients with mild asthma have shown that CD4+ T cells favour Th2 type immune responses in BALF, lung tissue, and blood, and secrete large amounts of cytokines, such as IL‐4, IL‐5, IL‐13 and IL‐9, while Th1‐type cytokines such as IFN‐γ, IL‐2 and IL‐12 are reduced." (PMID 33124760, 2020). "This demonstrates that initiating treatment of T2 inflammation with anti-IL5 or an agent which blocks IL4 and IL13 for subjects with asthma and/or atopic dermatitis who also have CSU, CSU symptoms may be improved." (PMID 32944029, 2020). "While they reported that serum SIRT1 levels were increased in OVA-sensitized and challenged mice model, SIRT1 levels were decreased in lung tissue, and more IL-4, IL-5, and IL-13 in BALF were found in the ovalbumin-induced asthma mouse model compared to the controls." (PMID 32823491, 2020). "Interestingly, increased peripheral blood‐derived fibrocyte CD14 expression following co‐culture is abrogated by IL‐4/IL‐13, which are expressed by mast cells present in the ASM in asthma." (PMID 33209301, 2020). "The highest serum IL-4 and IL-13 levels were found in asthma patients, but the intergroup differences were not significant." (PMID 33203095, 2020). "Altogether, our results indicate that Tespa1 can negatively regulate mast cell activity, and this event is related to the mast cell IL-4/STAT6 signaling pathway and could be therapeutically exploited to treat asthma attacks." (PMID 33228696, 2020). "Additionally, this drug inhibits the inflammation of asthma and COPD by suppressing the cytokine expression (i.e., IL-4 and IL-13)." (PMID 31952466, 2020).
asthma (continued). "BAMBI knock out mice model of asthma demonstrated significantly reduced airway hyperresponsiveness, pulmonary inflammation, broncho-alveolar lavage fluid (BALF) eosinophil count, as well as diminished IL-4, IL-5, IL-13 and IL-6." (PMID 32900903, 2020). "However, higher levels of IL-4, IL-17, IL-6, and IL-10 mRNA and lower levels of IFN-γ and TGF-β mRNA were observed in lungs of mice from the asthma group relative to those from the normal or PBS group." (PMID 32549755, 2020). "Here, we have analyzed the levels of cytokines such as IL-13, IFN-γ, TNF-α, IL-4, IL-5, and IL-1β and growth factors such as HGF, VEGF, and CSF2 or GM-CSF along with the estimation of serum S1P concentration in asthma patients compared with the healthy controls." (PMID 32637407, 2020). "Consistent with the interpretation that IL-4 is not a central driver of asthma, a number of clinical trials designed to selectively inhibit IL-4 in asthma patients have failed." (PMID 31120919, 2019). "This question is even more intriguing considering that, although IL-4 and IL-13 signaling do not have the same contribution in the pathogenesis of asthma and COPD, in both diseases, pendrin is similarly overexpressed." (PMID 30744098, 2019). "Furthermore, the cross-talking of the IL-4/13 signaling pathway and networks intermediated by transcription factor HIF-1α and FOXA1 play a crucial role in the pathogenesis of asthma." (PMID 31430856, 2019). "The intense release of IL-4 and IL-13 in the airways leads to airway narrowing, pulmonary inflammation, airway hyperresponsiveness (AHR), and increased mucus secretion, all typical features of asthma." (PMID 30744098, 2019). "Interleukin (IL)-4, IL-5, and IL-13, which are canonical type 2 cytokines produced by TH2 cells, prominently mediate the development of asthma and airway inflammation, manifesting as enhanced IgE-mediated sensitization, airway hyperreactivity (AHR), as well as eosinophil infiltration." (PMID 31921177, 2019). "ND mice with OVA-induced asthma had high-expression levels of IL-4 and IL-5, but naive HFD mice did not express significantly higher IL-4 or IL-5 levels in the lung tissue than naive ND mice." (PMID 31133649, 2019). "PM2.5 counteracts with IL-4-induced M2 polarization partially through mammalian target of rapamycin (mTOR) pathway, whereas in ovalbumin (OVA)-induced asthma, PM2.5 aggravates allergic inflammation by activating M2 macrophages and subsequent Th2-related immune responses." (PMID 31067702, 2019). "The incubation period of asthma, serum IFN-γ, IL-4, and LTB4 levels were tested and determined." (PMID 31531069, 2019). "Several direct links between those major compounds and the inhibition of the GATA-3/Th2 responses have been reported; for example, Camellia japonica oil suppressed asthma occurrence through the GATA-3, IL-4, and IL-5 pathways and its effective and major component is oleic acid." (PMID 30823378, 2019). "IL-4, IL-13, and IL-21, which promoted Th2 differentiation and allergic asthma, were also significantly increased in the CD4+ T cells from the asthma mouse model." (PMID 31231429, 2019). "Asthma pathogenesis primarily involves activation of eosinophils and CD4+ T cells, with downstream inflammation mediated mainly by Th2-type cytokines (IL-3, IL-4, IL-5, IL-9, IL-13, and granulocyte macrophage colony-stimulating factor)." (PMID 30126769, 2019). "Secreted IL-17 in splenic CD4+ T cells was significantly increased in the neutrophils-dominant asthma group compared to the conventional asthma group, but IL-4 was not obviously different in the neutrophilic group compared to the conventional group." (PMID 30150897, 2018). "Another putative mediator of severe asthma, IL-17F, has been shown to induce IGF-1 expression in bronchial epithelial cells along or by costimulation with IL-4 and IL-13, suggesting an important relationship among IGF-1 signaling, Th2, and Th17 cells in asthma." (PMID 30018981, 2018).
asthma (continued). "Moreover, supplementation with N. sativa oil improves interferon-γ (IFN-γ)/IL-4 balance and ACT in children with asthma." (PMID 30340634, 2018). "Many studies determined the effect of IL4, IL5 and IL13 in asthma pathogenesis there for making balance between TH1 and TH2 cytokines might be helpful in asthma management." (PMID 29743896, 2018). "The IL-4, IL-5 and IL-10 levels of allergic rhinitis, asthma and complication groups were significantly different from those of the control group (P<0.01) (Table-III).The IL-5 levels of allergic rhinitis and asthma groups were significantly different (P<0.01)." (PMID 30344593, 2018). "The levels of TGF-β and IL-4 production by non-stimulated PBMCs in patients with asthma were significantly higher than those of healthy controls (P <0.001 and P <0.03, respectively)." (PMID 30116273, 2018). "In our experiment, Treg cells isolated from patients with asthma expressed higher levels of Th2-type cytokines, such as IL-4, IL-5, and IL-13, rather than IFN-γ, the Th1-type cytokine." (PMID 30013989, 2018). "Other investigators have found a negative correlation between IFN-induction by RV and airway Th2 responses, including eosinophilia and detectable IL-4, in children with a history of asthma both with and without atopy." (PMID 29915592, 2018). "Recently, some studies have showed that dupilumab, a new anti-IL4/IL13 approach, could decrease asthma exacerbation and improve lung function." (PMID 29751569, 2018). "Multiple IL-4-inhibiting monoclonal antibody therapies have been tested in asthma clinical trials though the antibodies largely did not display efficacy." (PMID 28959799, 2017). "IL-4 expression is increased in AERD, asthma, CRSwNP, CRSsNP, and AR." (PMID 28959799, 2017). "Immunoreactivity of Th2-derived cytokines (IL-4, IL-5 and IL-13) was only weakly detected in the epithelium of nasal biopsy specimens of non-severe asthma patients with CRS (respectively)." (PMID 28199345, 2017). "Pathways exclusively enriched in AD included Cytokines and Inflammatory Responses, Th1/Th2 Differentiation, Dendritic Cell Pathway, Asthma, IL-12 STAT4 Signaling, CD40L Signaling, IL-4 Signaling, and CXCR3 Signaling, IL-2 STAT5 Signaling, CD8+ T-cell Signaling, and TCR Signaling." (PMID 28821884, 2017). "It is known that both IL4 and IL13 are involved type 2 responses, in IgE production in asthma, rhinitis and in eczema, as well as in the cellular inflammation of the three diseases as well as in the regulation of the epithelial barrier function in the skin, the airways, and type 2 responses." (PMID 28598986, 2017). "Interestingly, transdermal administration of NPRA siRNA nanoparticles significantly reduced eosinophilia, lung histopathology, pro-inflammatory cytokines IL-4 and IL-5, and AHR in an OVA-induced mouse asthma model." (PMID 28106744, 2017). "However, the relationships among IL-4, TRPC1 and mucus overproduction in bronchial epithelial cells (BECs) in asthma are poorly understood." (PMID 28931396, 2017). "However, the levels of serum IFN-γ, IL-4, and IL-17A levels were increased while the levels of IL-10 were increased by C5aRA treatment in RSV-infected, asthma and RSV-infected asthma mice." (PMID 29123203, 2017). "We did not analyze Th2 cytokines, such as IL-4, IL-5, or IL-13, and therefore we cannot exclude a certain involvement of Th2 response in the regulation of blood coagulation in asthma." (PMID 28429138, 2017). "Moreover, the levels of IFN-γ, IL-4, and IL-17A in serum, lung tissue, and BALF of C5aRA-treated RSV-infected asthma mice were also decreased, while the levels of IL-10 were increased." (PMID 29123203, 2017). "Decreased IL13RA1 expression is surprising in the context of asthma but this could be due to a compensatory response to continued eosinophilia and IL13/IL4 exposure in the lung." (PMID 29228930, 2017).
asthma (continued). "Concentrations of IL-4 (23.40 ± 0.78 pg/mL), IL-5 (15.05 ± 1.13 pg/mL), IL-13 (331.93 ± 61.74 pg/ml), IL-17 (72.21 ± 7.10 pg/ml) in BALF of mice in the wild-type group with asthma were significantly higher than that of control group (P < 0.05)." (PMID 28094276, 2017). "The primary inflammatory lesion of asthma is accompanied by the accumulation of cluster of differentiation 4+ (CD4+) Th2 cells and Eos’s in the airway mucosa and its secretion of a series of cytokines, mostly IL-4, IL-13, IL-5, and IL-9." (PMID 28678189, 2017). "In conclusion, the results of the present study indicated that the extract of Z. multiflora decreased pro-inflammatory cytokines in asthma (IL-4, IL-17, and TGF-β) whereas increased anti-inflammatory cytokine (IFN-γ) gene expression in splenocytes of experimentally-induced asthma in mice." (PMID 28824424, 2017). "After treating with prednisone or HFBP, IL-4 and TNF-α level significantly reduced (P < 0.05), suggesting that HFBP could inhibit IL-4 and TNF-α expression in the blood of asthma mice." (PMID 27143988, 2016). "In mice, it could be shown that the expression of TSLP, IL4, IL5 and IL13 induces atopic dermatitis as well as asthma, and IL5 knockout mice exposed to allergens are less prone than wild-type to develop skin eosinophilia and epidermal thickening." (PMID 27431613, 2016). "Blocking IL-13, but not IL-4, in animal models of asthma prevents the development of AHR after allergen, despite a strong eosinophilic response." (PMID 26334389, 2016). "Similarly, exposure to acute stressful life events in the context of chronic family stress has been linked to greater Th2 cytokine production, including levels of IL-4, IL-5, and IFN-gamma, among youth with asthma." (PMID 27965775, 2016). "Therefore, while other factors in addition to Th2 cells/cytokines are involved in the pathogenesis of asthma, it appears that WGP is specific in targeting the production of IL-4, IL-5, IL-13 and resulting eosinophilia in this model." (PMID 27390655, 2016). "Our findings with VVHE suggest that the V. vinifera fruits could act in asthma via its neutralizing effects on TH2 derived pro-inflammatory (TNF and IL-1β) and inflammatory (IL-4 and IL-5) cytokines, key elements in the pathophysiology of bronchial asthma." (PMID 27536321, 2016). "Extracts of Siegesbeckia glabrescens, a traditional medicinal plant in Korea, reduced mucus overproduction in airways in a asthma murine model, decreased the expression of iNOS and COX-2, reducing the number of inflammatory cells in BALF and the cytokine release (IL-4, IL-5 and IL-13)." (PMID 27445433, 2016). "Regarding the mechanism of PTP-RR down-regulation, MG-132, a proteasome inhibitor, abrogated IL-2/IL-4-induced reduction of PTP-RR protein expression, suggesting that a reduction in PTP-RR protein stability in severe asthma could be taking place." (PMID 27013170, 2016). "Two other studies comparing patients with asthma and healthy controls did not demonstrate any changes in the percentage of cells producing IL-4." (PMID 27799958, 2016). "In addition, among NF-κB-mediated cytokines, the secretion levels of IL-4, TNF-α, and eotaxin were significantly decreased by Rg3 in asthma tissues." (PMID 28116321, 2016). "Th2-type cytokines, including IL-4, IL-5, IL-13, IL-17, and IL-33 produced by activated CD4+ T-cells, enhance IgE production, eosinophil accumulation, and play a central role in the pathogenesis of asthma." (PMID 26385707, 2015). "Additionally, not only the infiltration of neutrophils and eosinophils but also the levels of IL‐4, IL‐5, and IL‐13 were reduced upon bvPLA2 treatment in OVA‐induced asthma mice." (PMID 26734460, 2015). "Since IL-4, LIGHT, LTBR, TGFβ, MMP-9, and NO are key mediators involved in the pathogenesis of allergy and asthma, the increase in their expression may contribute to the increased vulnerability and risk of asthma in the obese." (PMID 25642424, 2015).
asthma (continued). "IL-4 uses Janus kinases (JAKs) to initiate the signaling cascade and activate signal transducer and activator of transcription 6 (STAT6), consequently modulating allergic airway inflammation in asthma and other diseases." (PMID 26075216, 2015). "IL-4 directly promotes the polarization of naïve CD4+ T cell differentiation towards Th2 phenotype, which initiates inflammatory responses and propagates the symptoms of asthma." (PMID 26488300, 2015). "In the development of asthma, allergen-specific CD4+ T cells play a pivotal role by facilitating airway inflammation, which is largely mediated by type 2 T-helper (Th2) cytokines such as interleukin 4 (IL-4), IL-5 and IL-13." (PMID 26488300, 2015). "They found that gene signature profiles of Th2 (IL-13, IL-4) and Th17 (CXCL1, CXCL2, CXCL3, IL-8, CSF3) immune responses were inversely correlated in these samples suggesting a reciprocal regulation of these two pathways in asthma." (PMID 26561853, 2015). "IL-2, IL-4, IL-6, IL-17a and TNF-α were reported to be involved in asthma." (PMID 24735374, 2014). "We focused on the expression of IL-4, IFN-γ and ACSL3 mRNA in peripheral blood mononuclear cells (PBMC) of Saudi children with and without asthma and sought possible associations between cytokines and PAH levels." (PMID 24450480, 2014). "Recently, children (5–17 years) with severe therapy-resistant asthma had significantly increased BAL eosinophils compared control subjects but no increase in BAL fluid interleukin (IL)-4, IL-5, or IL-13 levels." (PMID 25905006, 2014). "Absence of Th2 cytokines IL4, IL-5 and IL-13 was also detected in school children (median age 12 years) with severe treatment-resistant asthma regardless of bronchial eosinophilia." (PMID 25905006, 2014). "Levels of IL-4 and interferon (IFN)-γ in the serum of mice exposed to P. aeruginosa were detected to determine the relationship between inhaled budesonide and Th1/Th2 immunoreactions for antibacterial host defense during asthma." (PMID 23387852, 2013). "Thus, IL-4/IL-13/signal transducer and activator of transcription 6 (STAT6) pathway becomes promising targets for asthma therapies by using IL-4 receptor antagonists and anti-IL-13 mAbs." (PMID 24204835, 2013). "Bronchoalveolar lavage fluid (BALF) from asthma patients contains high amounts of IL-4/IL-17A double-positive CD4+ T cells, and moderate-to-severe human asthma patients have more IL-17A-positive cells in bronchial submucosa than mild asthma patients." (PMID 23383714, 2013). "In the acute asthma model, we found a 55% reduction in IL-4 transcripts in the OVA-treated sPLA2-X knockout mice but no decrease in IL-5 or IL-13 transcripts." (PMID 23451035, 2013). "This is exemplified by the ability of only IL-4 to differentiate naïve CD4+ T cells into Th2 cells or the non-redundant role of IL-13 in parasite expulsion, allergic inflammation and asthma." (PMID 23027612, 2012). "Level of IL-4 secreted by NKT cells after proliferation activation in children with asthma group was significantly higher than normal control group (P < 0.01), particularly at 72 h; compared with asthma patients." (PMID 23008731, 2012). "Additionally, oral administration of ScLL reduced IL-4 and IL-5 levels in murine models of acute and chronic inflammation and lead to increased IFN-γ and IL-10 production in asthma inflammatory model, directing a shift from Th2- to Th1-biased immune response." (PMID 23107170, 2012). "Th2 cytokines, IL-4, IL-5 and IL-13 produced by activated CD4+ T cells, play a central role in the pathogenesis of asthma by controlling the key process of immunoglobulin E (IgE) production, growth of mast cells and the differentiation and activation of mast cells and eosinophils." (PMID 22514638, 2012).